LRP6 (LDL receptor related protein 6)
Diseases named in the same sentence as LRP6 in open-access papers (continued):
Sharing a sentence is not in itself a finding about the gene and the disease.
metabolic disease (4 papers, 2016 to 2025). A congenital disorder (due to inherited enzyme abnormality) or acquired (due to failure of a metabolically important organ) disorder resulting from an abnormal metabolic process. "For example, anti-β2-GPI antibodies recruit LRP6/PAR-2 complexes into rafts to induce prothrombotic responses, while raft dynamics regulate vascular function in metabolic disease through protein compartmentalization." (PMID 40568618, 2025).
neurodegenerative disease (4 papers, 2012 to 2023). A disorder of the central nervous system characterized by gradual and progressive loss of neural tissue and neurologic function. "Considering that dysregulation of the Wnt/β-catenin pathway has been reported in many neurodegenerative diseases, the LRP6 is a promising therapeutic target in other neurodegenerative diseases." (PMID 36908787, 2023). "Alternative strategies could aim at preventing DKK1 binding to the Wnt co-receptor LRP6 as suggested in other neurodegenerative diseases." (PMID 35397630, 2022). "In this study, we sought to further characterise NCI8642 activity, using biochemical and biophysical approaches, and to extend its characterization in relation to LRP6, given the prominent expression in brain of LRP6 and its relevance to the neurodegenerative diseases field." (PMID 27398238, 2012).
heart disease (2 papers, 2015 to 2022). "The disruption of LRP6 activities has been linked with several causes of heart disease, including increased serum LDL, glucose level, and triglycerides, indicating that LRP6 appears to be important for the regulation of glucose and lipid metabolism." (PMID 35052459, 2022).
adenocarcinoma (1 paper, 2011). A common cancer characterized by the presence of malignant glandular cells. "Transgenic mice that overexpress LRP6 in mammary epithelial cells develop mammary gland hyperplasia, but fail to develop adenocarcinoma suggesting the requirement for additional mechanisms for activating the Wnt pathway." (PMID 21767405, 2011).
kidney diseases (1 paper, 2021). "In this study, we systematically review the structure, regulation and function of LRP5 and LRP6 in the context of kidney diseases, with emphasis on their commonality and uniqueness in mediating Wnt signaling." (PMID 34026761, 2021). "In this review, we systematically discuss the similarity and divergence of LRP5 and LRP6 in mediating Wnt and other signaling in the context of kidney diseases." (PMID 34026761, 2021). "Although LRP5 and LRP6 are co-receptors in canonical Wnt pathway, their exact role in kidney disease is unclear." (PMID 34026761, 2021). "While plentiful excellent reviews on Wnt signaling in human diseases, particularly the kidney disorders, have been published, relatively less is reported on the regulation and divergent functions of LRP5 and LRP6." (PMID 34026761, 2021).
neurological diseases (1 paper, 2022). "Previous studies have reported that low-density lipoprotein receptor-related protein 6 (LRP6) exerts neuroprotection in several neurological diseases." (PMID 35419167, 2022). "In recent years, the role of LRP6 in neurological diseases has also been gradually investigated." (PMID 35419167, 2022). "As research progressed, it was found that LRP6 activation could participate in neuroprotection in neurological disorders." (PMID 35419167, 2022).
LRP6 also shares sentences with these, for which no sentence is quoted: osteoarthritis (5 papers); Hypodontia (4); hypertriglyceridemia (3); microphthalmia (3); retinoblastoma (3); carotid atherosclerosis (2); diabetes mellitus type 2 (2); Hepatic steatosis (2); oral squamous cell carcinoma (2); orofacial cleft (2); renal fibrosis (2); acute kidney injury (1); acute myocardial infarction (1); alcoholic liver diseases (1); Apert syndrome (1); Atrophy (1); autism spectrum disorder (1); Blindness (1); bone cancer (1); chondrosarcoma (1); colorectal adenocarcinoma (1); COVID-19 (1); craniodiaphyseal dysplasia (1); craniosynostosis (1); dementia (1); demyelination (1); essential hypertension (1); Familial exudative vitreoretinopathy (1); generalized epilepsy (1); Glucose intolerance (1).
A further 43 diseases each share a sentence with LRP6 in 1 paper.